MMP9 (matrix metallopeptidase 9)
Diseases named in the same sentence as MMP9 in open-access papers (continued):
Sharing a sentence is not in itself a finding about the gene and the disease.
glioblastoma (203 papers, 2006 to 2026). The most malignant astrocytic tumor (WHO grade IV). "Other reports, however, associate high MMP-9 levels with smaller edema volumes in glioblastomas and specific brain locations." (PMID 41573658, 2025). "In conclusion, the findings of this study indicate that high intra-tumoral and pre-operative sera MMP-9 levels, along with intra-tumoral MMP-9 activity, are associated with poorer OS in glioblastoma and BM patients." (PMID 41573658, 2025). "The aim of this study was to analyze the relationship between tumor angiogenesis in glioblastomas in association with MMP-9 immunoexpression." (PMID 39684754, 2024). "This study aimed to apply pathomics to predict Matrix metalloproteinase 9 (MMP9) expression in glioblastoma (GBM) and investigate the underlying molecular mechanisms associated with pathomics." (PMID 38956384, 2024). "Jiguet-Jiglaire tested patients with recurrent glioblastoma prior to treatment and found decreased plasma levels of MMP-9 associated with increased OS." (PMID 36765669, 2023). "Bevacizumab treatment led to increased expression and enzymatic activity of MMP-2 and MMP-9, common metalloproteinases associated with neovascularization of tumors, in glioblastoma cells both in vitro and in vivo." (PMID 33804681, 2021). "Matrix metalloproteinase-2 (72 kDa, MMP-2, also termed gelatinase A) and MMP-9 (94 kDa, also termed gelatinase B) are proteolytic collagenases strongly associated with glioblastoma growth and invasion." (PMID 23594434, 2013). "Low basal MMP-9 expression occurs in normal brain tissue, but high expression levels are induced in glioblastomas, and are linked to increased tumour cell proliferation." (PMID 23039130, 2012). "recently linked sera MMP-9 and perfusion-weighted MRI parameters to glioblastoma recurrence." (PMID 41573658, 2025). "MMP-9 level was intensely associated with glioblastoma grade." (PMID 29423667, 2018). "Recently, case report studies on childhood glioblastoma suggested that MMP-9 upregulation could be associated with tumor resistance to temozolomide at relapse." (PMID 23183822, 2012). "Aberrant MMP-9 expression is also implicated in the glioblastoma angiogenesis process." (PMID 23039130, 2012). "Similarly, PIK3R1 knockdown reduced MMP2 and uPA levels in neurospheres, and reduced MMP2 and MMP9 levels in D54 cells, and reduction of the levels of these proteins has been shown to cause reduced migratory and invasive capacity in glioblastoma cells." (PMID 22064833, 2011). "MMP9 is overexpressed in various cancers, including in glioblastoma, and its overexpression in GBM is associated with a poor prognosis due to tumor progression and cancer recurrence." (PMID 38906916, 2024). "Two recent studies using mouse models of mammary carcinoma and glioblastoma (GBM) also support the essential role of MMP-9 when associated with BM cells or macrophages in increasing VEGF bioavailability and initiating tumor vascularization." (PMID 24314323, 2013). "Collectively, these results suggest that GAD1 inhibits the expression of Cyclin D1 and MMP9 via the p-GSK3β/β-catenin pathway, thereby impeding glioblastoma progression." (PMID 41844572, 2026). "The previous literature has reported a trend of down-regulation of the MMP9 gene at both mRNA and protein expression levels in glioblastoma patients treated with radiotherapy combined with TMZ." (PMID 41438689, 2026). "Clinical and imaging data from 27 glioblastoma patients and 30 individuals with brain metastases were analyzed, measuring and comparing their intra-tumoral and sera MMP-9 levels and activity against those of 12 meningioma patients and 23 healthy controls." (PMID 41573658, 2025). "MMP-9 activity showed a similar pattern, being notably higher in glioblastoma and brain metastases than in meningioma (p=0.004)." (PMID 41573658, 2025).
glioblastoma (continued). "Previously performed studies showed the presence of MMP-2 and MMP-9 in two other culture media of the glioblastoma line, GAMG and 8-MG-BA, and the activity of both enzymes was twice as high in the medium collected from 8-MG-BA." (PMID 40141020, 2025). "Preoperative sera MMP-9 levels were significantly higher in glioblastoma patients (median: 2.8 ng/ml, IQR: 2.1-3.7, p<0.001) compared to BM (1.8 ng/ml, IQR: 1.3-2.3), meningioma (1.2 ng/ml, IQR: 0.9-1.4), and healthy individuals (0.8 ng/ml, IQR: 0.6-1.0)." (PMID 41573658, 2025). "This study examines the role of MMP-9 in glioblastoma and BMs), emphasizing its potential as a biomarker for disease monitoring and prognosis." (PMID 41573658, 2025). "Glioblastoma and BM patients with low serum MMP-9 had significantly longer OS (15.8 months vs. 8.4 months, p=0.022)." (PMID 41573658, 2025). "The overexpression of MMPs, particularly MMP-9, is markedly observed in glioblastoma multiforme (GBM), an aggressive primary brain tumor known for its diffuse and infiltrative nature." (PMID 40019229, 2025). "So far, several clinical studies have examined how MMP-9 affects treatment outcomes in metastatic cancer and glioblastoma." (PMID 41573658, 2025). "This study examines intra-tumoral and sera MMP-9 levels and their correlation with overall survival (OS) in patients with glioblastoma and BM." (PMID 41573658, 2025). "Gelatin zymography analysis visually confirmed elevated sera MMP-9 levels in glioblastoma and BM compared to meningioma and healthy controls." (PMID 41573658, 2025). "The results indicate that intra-tumoral and preoperative serum MMP-9 levels are significantly higher in glioblastoma and BM patients than in those with meningioma and healthy individuals." (PMID 41573658, 2025). "The assessment of intra-tumoral MMP-9 levels revealed significantly higher concentrations in glioblastoma (8 ng/ml) and brain metastases (4 ng/ml) compared to meningioma (1 ng/ml; p<0.001)." (PMID 41573658, 2025). "Representative gelatin zymography shows increased MMP-9 in glioblastoma and BM serum samples compared to low-grade astrocytoma and healthy control sera." (PMID 41573658, 2025). "This study builds on prior research by demonstrating that glioblastoma patients exhibit significantly higher intra-tumoral and sera MMP-9 levels." (PMID 41573658, 2025). "In glioblastoma, elevated MMP-9 levels strongly correlate with enhanced angiogenesis and tumor invasiveness." (PMID 40630800, 2025). "A key finding in this study is that glioblastoma and BM patients with low sera MMP-9 levels experienced significantly longer OS (15.8 months vs. 8.4 months in those with high levels, p=0.022)." (PMID 41573658, 2025). "Matrix metalloproteinase 9 (MMP-9) has been shown to promote glioblastoma invasion and the spread of brain metastases (BM)." (PMID 41573658, 2025). "The bioresponsive material selectively inhibits MMP‐2 versus MMP‐9 in glioblastoma microenvironment." (PMID 40556034, 2025). "Univariate analysis showed that high sera MMP-9 levels significantly contributed to reduced OS in glioblastoma and BM patients (p=0.024)." (PMID 41573658, 2025). "It was observed that as age increased, MMP-9 immunoexpression was more pronounced in the studied glioblastomas." (PMID 39684754, 2024). "The immunoexpression of MMP-9, which plays a role in remodeling the tumor microenvironment, was present in approximately half of the studied glioblastomas." (PMID 39684754, 2024). "In glioblastoma patients, the release of MMP-9 by tumor-infiltrating neutrophils contributes to the efficacy of bevacizumab." (PMID 39712025, 2024). "They observed elevated expression of MMP9 and MMP2 in anaplastic astrocytomas, oligodendrogliomas, and glioblastomas compared to meningiomas and other benign tumors, indicating a direct relation between MMP9 and MMP2 expression and malignant behavior." (PMID 38474106, 2024).
glioblastoma (continued). "Although the MMP9 gene alone is considered a prognostic marker for glioblastomas, we are the only ones to point to the role of the malignancy grade in relation to TIMP4." (PMID 38474106, 2024). "The tumor microenvironment plays a critical role in shaping the prognosis of glioblastoma, with matrix metalloproteinase 9 (MMP-9) serving as a key regulator within this microenvironment." (PMID 39684754, 2024). "We found eight deregulated genes in the glioblastoma group compared to the benign meningioma group, with only MMP9 (FC = 2.55; p = 0.09) and TIMP4 (7.28; p < 0.0001) upregulated in an aggressive form." (PMID 38474106, 2024). "Concerning the relationship with MMP-9, cases without MMP-9 expression had relatively higher median tumor volumes (43.5 cm3 vs. 39.8 cm3) compared to glioblastomas with MMP-9 expression." (PMID 39684754, 2024). "We found a relation between low MMP-9 level in sEVs (<28 ppm) and improved survival (8-month advantage) of glioblastoma patients, and MMP-9 levels showed a positive correlation with aggressiveness." (PMID 36765669, 2023). "Similar research is needed in the glioblastoma context since the invasion and MMP-9 expression were also reduced in our present study following WWOX overexpression." (PMID 36979157, 2023). "We found high expression of ICAM1 and high expression of MMP9 was related to shorter survival in glioblastoma multiforme patients." (PMID 37732732, 2023). "The inhibition of Erk and p38 was then found to be involved in MMP-2 and MMP-9 expression, which revealed naringenin’s ability to inhibit the migration of glioblastoma cells." (PMID 36839156, 2023). "For example, in human fibrosarcoma HT-1080 and HCC SK-Hep-1, cells express both MMP2 and MMP9, and glioblastoma T-98G cells express MMP2 but MMP9 only after stimulation with PMA." (PMID 36677584, 2023). "The phase I study is the first step to analyse the tolerance, determine the recommended dose of the combination, and explore the impact of GS5745 on MMP-9 plasma levels and multimodal imaging in patients with recurrent glioblastoma (NCT03631836)." (PMID 36765669, 2023). "Wang et.al firstly confirmed that EIF4A3 involved in circMMP9 cyclization by uniting with its matrix metalloproteinase-9 (MMP-9) mRNA transcript in glioblastoma multiforme." (PMID 37626035, 2023). "Taken together, these results confirm that MMP9 is indeed expressed by immune cells infiltrating the glioblastoma microenvironment." (PMID 34980260, 2022). "Then we observed that the MMP9 plasma level significantly decreased after glioblastoma resection (p = 0.03)." (PMID 34980260, 2022). "Then, we showed that MMP9 was mainly released by the tumor-infiltrating neutrophils of the glioblastoma microenvironment." (PMID 34980260, 2022). "Then, exploring the source of MMP in the tumors, we showed that the MMP9 plasma level was significantly higher in glioblastoma patients than in control subjects, decreased after tumor resection, and was correlated with MMP9 tumor expression." (PMID 34980260, 2022). "α-Hispanolol induced apoptosis and inhibits the cell migration of glioblastoma cells by a decreased level of MMP-9." (PMID 35723293, 2022). "For example, it was found that EIF4A3 directly combines with the MMP9 mRNA transcript, accelerates circMMP9 cyclization, and increases circMMP9 levels in glioblastoma multiforme." (PMID 36138395, 2022). "The evaluation of the anticancer potential of honey bee (Apis mellifera) venom (BV) consisting of the inhibition of MMP-2 and MMP-9 secretion in a glioblastoma cell culture model was the aim of the study." (PMID 35221898, 2022). "It was also demonstrated that the use of a dominant negative mutant of ERK1, in which the conserved residue Lys71 was replaced by Arg, resulted in the reduction of MMP9 levels in glioblastoma cells." (PMID 35406619, 2022).
glioblastoma (continued). "TPA (12-O-tetradecanoylphorbol-13-acetate) has been reported to activate PKCα/ERK/NF-κB-dependent matrix metalloproteinase 9 (MMP-9) expression and elicit glioblastoma cell migration, which can be prevented through downregulating PKCα expression." (PMID 35267413, 2022). "A prospective local cohort of 38 patients with newly diagnosed glioblastoma was developed for analysis of tumor characteristics by magnetic resonance imaging and measurement of plasma and tumor levels of MMP9 and MMP2." (PMID 34980260, 2022). "The involvement of MMP-2 and MMP-9 in the pathogenesis of various kinds of cancers including glioblastoma is well documented." (PMID 35221898, 2022). "To determine the origin of MMP9 in glioblastoma, we first analyzed its expression by immunohistochemistry." (PMID 34980260, 2022). "Silencing of siRNA genes for cathepsin B and MMP9 in glioblastoma SNB19 cells cocultured with microvascular endothelial cells manifested as inhibition of microvessel network formation induced by tumor cells." (PMID 35406619, 2022). "We previously identified matrix metalloproteinase 2 (MMP2) and MMP9 plasma levels as candidate biomarkers of bevacizumab activity in patients with recurrent glioblastoma." (PMID 34980260, 2022). "First, we showed that the baseline MMP9 plasma level was higher in glioblastoma patients than in patients operated for cerebral aneurysm or healthy controls (p = 0.006)." (PMID 34980260, 2022). "Then, because MMP9 was reported to be involved in invasive processes through extracellular matrix remodeling, we analyzed the infiltrative pattern of glioblastoma using the ratio enhancement volume/FLAIR volume." (PMID 34980260, 2022). "After normalization by cell frequency and mean fluorescence intensity shift, the neutrophils appeared to be the main origin of MMP9 expression in IDHwt glioblastoma (p = 0.008)." (PMID 34980260, 2022). "To determine which immune population was responsible for MMP9 expression in the glioblastoma microenvironment, we analyzed five fresh IDHwt glioblastoma samples by flow cytometry using a large panel of antibodies." (PMID 34980260, 2022). "In the present post hoc analysis of a phase III trial (AVAglio), we showed that baseline MMP9 plasma level is predictive of bevacizumab efficacy in patients with newly diagnosed glioblastoma." (PMID 34980260, 2022). "Considering this fact, the aim of the current study was to examine the in vitro influence of BV on cell viability and the BV induced secretion of MMP-2 and MMP-9 by glioblastoma cell lines (GAMG, 8-MG-BA) vs. hippocampal cells (HT-22)." (PMID 35221898, 2022). "The aim of this study was to assess the predictive value of MMP2 and MMP9 in a randomized phase III trial in patients with newly diagnosed glioblastoma and to explore their tumor source." (PMID 34980260, 2022). "In the literature, miR-671-3p has also been shown to regulate particles in the progression of glioblastoma by its effect on CKAP4 (cytoskeleton-associated protein 4) and MMP-9 (matrix metallopeptidase 9)." (PMID 35456388, 2022). "Circ_0001162 that was derived from the matrix metalloproteinase 9 (MMP9) gene has been reported as an tumorigenic factor in glioblastoma through targeting miR-124." (PMID 34057019, 2021). "Previous reports also showed that MMP9 expression and invasion of glioblastoma (C6) cells were blocked by LY294002." (PMID 34209215, 2021). "The flavonoid-based synthetic PI3K inhibitor, LY294002, was found to inhibit expression of MMP9 and invasion of glioblastoma (C6) cells." (PMID 33958632, 2021). "It has been reported that naringin inhibits the expression of MMP-2 and MMP-9 in human glioblastoma." (PMID 34054546, 2021). "Eukaryotic initiation factor 4A3 (eIF4A3) induces circMMP9 expression by binding to MMP9 pre‐mRNA and also promotes glioblastoma multiform proliferation and metastasis." (PMID 33687144, 2021).
glioblastoma (continued). "It has been found that in a xenograft model, the hemopexin domain of MMP-9 was an inhibiting factor in angiogenesis, as demonstrated by decreased invasion of glioblastoma cells overexpressing the MMP-9 hemopexin domain." (PMID 33803206, 2021). "used a miRNA microarray in 60 glioblastoma multiforme samples to show that miR-885-5p has a high correlation with MMP-9 expression." (PMID 33430870, 2021). "EIF4A3 bound to the MMP9 mRNA transcript, inducing circMMP9 cyclization and increasing circMMP9 expression in glioblastoma multiforme." (PMID 34930906, 2021). "Immunofluorescence demonstrated that astrocytes incorporate glioblastoma EVs and subsequently increase their secretion of active MMP9." (PMID 32033611, 2020). "MiR-7 also regulates theexpression of matrix metalloproteinase (MMP)-2 and MMP-9 in coloncancer/glioblastoma cells (Wu etal., 2011; Zeng etal., 2016)." (PMID 32167127, 2020). "MMP2 and MMP9 belonging to the gelatinase subfamily are abundantly expressed and directly related to the degree of glioblastoma malignancy." (PMID 31986121, 2020). "We also demonstrated that CD147 was increased in the EVs of irradiated glioblastoma cells, contributing to increased active MMP9 release in astrocytes recipient of the vesicles." (PMID 32033611, 2020). "Here, we also found that the activities of MMP-2 and MMP-9 are involved in glioblastoma cells’ invasion, as the activities of MMP-2 and MMP-9 were impaired in CrataBL-treated cocultures, but remained unchanged in CrataBL-treated MSC and U87 cell monocultures." (PMID 31167364, 2019). "In addition, α-H also increased TIMP-1 expression and inhibited mRNA expression and protein levels of MMP-2 and MMP-9 and hence their enzymatic activities, which may be associated to the reduced migration and invasion capacities of glioblastoma cells exerted by α-H." (PMID 31551765, 2019). "In this study, we confirmed that GADD45A reduced the expression of β-catenin and MMP-9 in IDH1R132H glioblastoma cells, providing a deeper insight into how β-catenin is regulated in these tumors." (PMID 28445981, 2017). "Consistent with a role of CD44, MMP9 and CHI3L1 in aggressive glioblastoma properties, low expression of the three genes was associated with better outcome in TCGA samples." (PMID 28036297, 2017). "In Western blot analysis, the expression levels of MMP-2 and MMP-9 were decreased in the glioblastoma cells following treatment with HES in a dose-dependent manner." (PMID 29181405, 2017). "The results obtained in the present study signified the importance of some genes, such as COL3A1, FN1, and MMP9, for glioblastoma." (PMID 28191466, 2017). "Inhibition of miR-148a significantly reduced β-catenin, EMT marker, and MMP-9 expression in IDH1R132H glioblastoma cells and these effects were prevented by GADD45A knockdown." (PMID 28445981, 2017). "Elevated level of MMP-9 is documented in glioblastoma and silencing of MMP-9 inhibits tumor invasion." (PMID 26940200, 2016). "MMP9 was the only significant prognostic factor in three datasets for primary glioblastoma patients." (PMID 27022952, 2016). "In one study, Polish honeys were shown to decrease MMP-2 and MMP-9 activity in the glioblastoma cell line U87MG." (PMID 28933410, 2016). "Several studies address the fact that MMPs especially MMP-2 and MMP-9 overexpressed in glioblastoma cells compared with normal brain tissue." (PMID 27026929, 2016). "Inhibition of uPAR and MMP9 expression has been shown to inhibit invasion in a glioblastoma cell line." (PMID 25180193, 2014). "Methylation of the miR-211 gene up-regulates gelatinase B/MMP-9 expression in glioblastoma stem cells and increases their resistance to radiotherapy and chemotherapy-induced death." (PMID 24473089, 2014). "Recently, the MMP-9-specific miRNA expression profile was established via miRNA microarrays as a potential target of anti-invasion therapy in glioblastoma." (PMID 23183822, 2012).